TLR2 (toll like receptor 2)
Diseases named in the same sentence as TLR2 in open-access papers (continued):
Sharing a sentence is not in itself a finding about the gene and the disease.
glioblastoma (11 papers, 2014 to 2025). The most malignant astrocytic tumor (WHO grade IV). "HMGB1 generated from tumor tissues activates CD8+ T cells against glioblastoma and initiates TLR2 signaling." (PMID 40727443, 2025). "TLR2 expressed in microglia can promote glioblastoma progression by up-regulating the expression of MT1-MMP in microglia." (PMID 33193404, 2020). "Despite low TLR4 expression glioblastoma stem cells express high levels of TLR2, and its stimulation by high-mobility group box 1 (HMGB1) enhanced the stemness markers of those cells." (PMID 31695691, 2019). "Toll-like receptor 2 (TLR2), one of the HMBG1 receptors, has been considered to involve in the production of NETs, and HMGB1-mediated TLR2 signaling plays a critical role in eliciting glioblastoma regression, suggesting the prospect of NETs in malignant brain tumors." (PMID 34868063, 2021). "The release of HMGB1 as a result of viral-derived ganciclovir tumor cell death activates TLR2 on DCs (immunogenic cell death), resulting in an efficient processing and cross-presentation of tumor antigens leading to tumor regression in a glioblastoma mouse model." (PMID 31695691, 2019). "TLR2 plays an important role in the induction of tumor regression, which has been demonstrated in a mouse model of glioblastoma multiforme where blocking HMGB1-mediated TLR2 signaling via tumor-infiltrating myeloid DCs resulted in a loss of therapeutic efficacy." (PMID 24744758, 2014). "We noted an overlap of up-regulated genes with an immune signature reported in a glioblastoma profiling study, including MHC class I and II genes, the complement factors C1QA/B/C, FCGR3A, B2M, SOCS3, TLR2 and CTSH." (PMID 25593989, 2014). "ANXA2m is overexpressed by murine glioblastoma GL261 cells grown under 5 % O2, but not atmospheric 20 % O2, and acts as an adjuvant by inducing murine and human DC maturation through TLR2." (PMID 26885373, 2016).
oral cancer (11 papers, 2011 to 2025). "Polymorphisms in TLR7 and TLR5 were recently associated with oral cancer suppression, while polymorphisms in TLR4 and TLR2 were associated with oral cancer progression." (PMID 38850110, 2024). "Individuals with the combined SNPs of TLR2 and TLR4 had an elevated risk of bacteria-related oral cancer (odds ratio = 1.46; 95% confidence interval: 1.23–1.75)." (PMID 33668218, 2021). "In this regard it is of interest that, TLR2/6 is also activated by a host matrix protein versican, the expression of which predicts progression and poor prognosis in oral cancer." (PMID 29467931, 2018). "P. gingivalis also promotes proliferation of oral carcinoma cells in a TLR2-dependent manner." (PMID 32824786, 2020). "TLR2 and TLR4 are found in several cell types including oral epithelial cell, gingival fibroblast and with overexpression by oral cancer cells." (PMID 32825570, 2020).
C. perfringens infection (10 papers, 2018 to 2023). "However, the increased mRNA expression (TLR1 and TLR2) caused by C. perfringens infection was effectively inhibited (p < 0.01) by co-incubation with L. plantarum Lac16." (PMID 34830269, 2021). "The results suggest that TLR2 plays a complementary role to TLR4 during C. perfringens infection." (PMID 33763386, 2021). "During C. perfringens infection, bacterial components stimulate TLR2." (PMID 31480318, 2019). "Thus the activation of not only TLR2 but also TLR4 by α-toxin should be important to understand clinical features of C. perfringens infection." (PMID 30729183, 2019). "Docking was performed against TLR1/TLR2 and TLR4/MD2, as they have been widely reported to be important in the innate defense against C. perfringens infection in chickens and mice, although little is known in humans." (PMID 36110855, 2022). "Real-time PCR confirmed that host TLR2 and NLRP3 inflammasome genes were induced in response to C. perfringens infection." (PMID 29588405, 2018).
encephalitis (10 papers, 2007 to 2023). An acute inflammatory process affecting the brain parenchyma. "Dual TLR2/9 ablation resulted in the highly enhanced mortality with exacerbated symptoms of encephalitis compared with TLR2 or TLR9 deficiency alone, coinciding with highly increased viral load in central nervous system tissues." (PMID 29760708, 2018). "C57BL/6 mice have a mortality rate of only 10% while TLR2/9−/− mice have a 100% mortality rate between the 5th and 8th day after infection with signs of encephalitis (prostration, ruffled fur, hunched posture, and posterior paw paralysis)." (PMID 28222752, 2017). "In a recent report, TLR2-deficient neonatal mice were found to be less susceptible to encephalitis caused by HSV, suggesting that TLR2 plays an important role in disease pathogenesis." (PMID 17470292, 2007). "Rather TLR2 may contribute to viral pathogenesis during HSV infection, evidenced by the finding that TLR2-deficient mice are resistant to viral encephalitis despite displaying similar viral loads compared with the wild type mice." (PMID 23435233, 2013). "Moreover, it was demonstrated that the adaptor molecule MyD88 or the TLR2 and TLR9 receptors together are crucial to host survival, since mice deficient in these molecules succumb to HSV-1 infection with encephalitis, whereas wild-type (WT) C57BL/6 mice can control the infection and survive." (PMID 28222752, 2017). "Using this model, mice with single deletions in specific TLRs, such as TLR2, TLR7, TLR9, or TLR13 were fully capable of controlling bacterial replication in the lung, but 30 to 45% of them developed encephalitis late during infection." (PMID 32209688, 2020). "Proteomics analysis showed activation of inflammation pathways including JAK-STAT signaling, TLR1/TLR2 cascade, NFκB phosphorylation and IKK complex, as well as other innate immunity components that support the monocytic inflammation nature of the encephalitis." (PMID 36609561, 2023). "Moreover, expression of TLR2 is enhanced in the hindbrain of mice infected with HSV-2 whereas TLR2 activation during acute HSV-1 encephalitis in neonatal and adult mice significantly boost the inflammatory damage in the nervous tissue." (PMID 30254622, 2018). "The ablation of TLR2, TLR7, and TLR9 molecules did not significantly affect the progression of encephalitis caused by JEV." (PMID 25188232, 2014).
endothelial dysfunction (10 papers, 2012 to 2026). In vascular diseases, endothelial dysfunction is a systemic pathological state of the endothelium (the inner lining of blood vessels) and can be broadly defined as an imbalance between vasodilating and vasoconstricting substances produced by (or acting on) the endothelium. "This study examined the role of TLR2 and 4 in regulating inflammation and endothelial dysfunction when exposed to fluctuating glucose concentrations." (PMID 25303153, 2014). "In addition, abnormal HDL-C can contribute to endothelial dysfunction and innate immunity via activation of Toll-like receptor-2 in CKD patients." (PMID 29212518, 2017). "Also, previous studies indicate that the TLR2 receptor agonist, LTA, induces endothelial dysfunction: therefore, we studied the relationship between TLR2 activation and ROS/RNS production." (PMID 23166614, 2012). "Thus, we hypothesized that the activation of TLR2 and 4 when exposed to glucose fluctuations may provide a mechanistic link between inflammation and endothelial dysfunction in microvascular complications." (PMID 25303153, 2014). "The binding of HMGB1 to receptors such as TLR2, TLR4, and RAGE triggers inflammatory pathways that contribute to endothelial dysfunction and vascular inflammation." (PMID 40361188, 2025). "The NP’s interactions with host cell components, such as Toll-like receptor 2 (TLR2) and various signaling pathways, including NF-κB and MAPK, underscore its significant impact on endothelial dysfunction and immune response modulation." (PMID 40416618, 2025). "There is a paucity of data examining the role of TLR2 and 4 in glucose and HMGB1 induced endothelial dysfunction." (PMID 25303153, 2014). "Released during necrosis, apoptosis, and neutrophil extracellular trap (NET) formation, histones act as damage-associated molecular patterns (DAMPs), engaging receptors such as Toll-like receptors (TLR2, TLR4, TLR9) to trigger endothelial dysfunction, platelet activation, and cytokine release." (PMID 41993174, 2026). "Activation of the TLR2 and TLR4 pathways by dentilisin leads to the upregulation of MyD88-dependent signaling, which triggers pro-inflammatory cytokines and excessive endothelial cell activation, contributing to endothelial dysfunction and CVD pathogenesis." (PMID 40136726, 2025).
renal fibrosis (10 papers, 2009 to 2026). A final common manifestation of a wide variety of chronic kidney diseases characterized by glomerulosclerosis and tubulointerstitial fibrosis. "In conclusion, on 2 consecutive days in a 100 mg/kg STZ-induced renal fibrosis mouse model, our results demonstrate that aggravated renal fibrosis is positively associated with the activation of HMGB1/TLR2/4 signaling." (PMID 36448056, 2022). "The unilateral ureteral obstruction (UUO) model is often used in the context of renal fibrosis and data from TLR2– or TLR4-deficient mice propose that TLR signaling contributes to postobstructive renal inflammation, tubular atrophy, and interstitial fibrosis." (PMID 21544241, 2011). "HMGB1 participates in the formation of renal fibrosis in the development of CKD through binding to TLR2 and RAGE." (PMID 30532765, 2018). "TLR2 has also been involved in renal fibrosis after unilateral ureteral obstruction, and has been suggested to be important for Leptospira-induced fibrosis." (PMID 24498450, 2014). "Although we demonstrated in a previous study that at day-3 p.i. the up-regulation of iNOS is decreased in TLR2/4dko mice, TLR2/4dko mice still developed renal fibrosis." (PMID 24498450, 2014). "In this study, although the results from the study confirm that the activation of HMGB1/TLR2/4 contributes to the renal fibrosis process, the effect of the suppression of HMGB1 expression remains unclear and future experiments are needed." (PMID 36448056, 2022). "Although Chop deficiency did not affect UUO-induced TLR2 and RAGE expression, UUO induced a significant upregulation for both TLR2 and RAGE, indicating that additional factors other than CHOP-associated HMGB1 are also implicated in the pathogenesis of renal fibrosis." (PMID 26247732, 2015). "On the other hand, it is likely that some pro-fibrotic factors such as HMGB1 or HMGB1/TLR2 inhibition may be more important than TLR2 alone inhibition in interfering with renal fibrosis." (PMID 25284457, 2014). "Interestingly, it seems that TLR4 was probably the primary receptor for Hmgb1 in our model of UUO-induced renal fibrosis as Chop deficiency did not affect UUO-induced expression of TLR2 and RAGE but attenuated TLR4 by twofold." (PMID 26247732, 2015). "Renal function of adult Tlr2-/- mice is enhanced as compared to WT controls while TH2 cytokine production and renal fibrosis following UUO are reduced." (PMID 38015955, 2023). "Although the activation of HMGB-mediated TLR2/4 signaling has been analyzed in several mouse models of DKD, the correlation between HMGB1 activity and the progression of renal fibrosis is not well known." (PMID 36448056, 2022). "However, our in vivo results showed that renal fibrosis is still present in TLR2/4 double deficient mice, excluding any major contribution of these receptors, and confirmed the fact that TLR2 agonists such as LipL32 are not major players in triggering renal interstitial fibrosis." (PMID 24498450, 2014). "Our results demonstrate that TLR2 does play an essential role neither in kidney inflammation nor in the development of renal fibrosis following neonatal UUO." (PMID 38015955, 2023). "These rather unexpected results are in accordance with the recent work of Anders's group showing that post obstructive renal fibrosis is independent of TLR2, TLR9 and MyD88." (PMID 24498450, 2014). "It reveals that TLR2 initiates a renal inflammatory response during obstructive nephropathy, but does not play a significant role in the development of renal fibrosis." (PMID 25284457, 2014). "Our present finding, together with the fact that TLR2 is not involved in Leptospira induced renal fibrosis, strongly suggests that in vivo, LipL32 is not involved in the fibrogenesis process." (PMID 24498450, 2014). "We therefore conclude that SIGIRR is redundant in UUO-induced renal fibrosis because TLR2-, TLR9- and MyD88 signaling do not significantly contribute to this model." (PMID 21544241, 2011).
renal fibrosis (continued). "The expression and function of TLR2 during renal fibrosis and chronic inflammation has however not yet been elucidated." (PMID 19479087, 2009). "We therefore conclude that TLR2 does not attenuate renal fibrosis in the neonatal kidney with UUO." (PMID 38015955, 2023). "However, TLR2 does not influence inflammatory responses or development of renal fibrosis after UUO." (PMID 38015955, 2023).
steatosis (10 papers, 2013 to 2025). Increased lipid within the cytoplasm of cells. "Compared with CRIg−/− mice, mice with disruptions in both CRIg and Tlr2 had less liver injury, steatosis, and inflammation—similar to ethanol-fed wild-type mice." (PMID 34887405, 2021). "The results demonstrated that in the SS group, pathways including TNF-JNK signaling pathway,IL-1/IL-1R-JNK signaling cascade, and TLR2/4-MAPK signaling axis collectively indicate the role of pro-inflammatory signaling in driving steatosis progression toward fibrosis." (PMID 40918148, 2025). "TLR2- and 4-mediated signaling has emerged as a major mechanism involved in regulating inflammatory responses in mouse models of HFD-induced steatosis." (PMID 23533470, 2013). "Vitamin D deficiency deteriorated MASLD progression through the activation of toll-like receptor 2 (TLR2) and TLR4 through the CD14/human LPS-binding protein (LBP), subsequently triggering downstream inflammatory signaling molecules that result in steatosis and inflammation." (PMID 38732118, 2024). "Chimeric mice with Kupffer cells that do not express MYD88/TRIF or TLR2 were protected from E. faecalis -exacerbated alcoholic liver injury, steatosis, inflammation, and fibrosis, compared with chimeric mice with WT Kupffer cells." (PMID 29038503, 2017). "TLR2 knockout mice fed a HFD showed improvement in glucose tolerance and a decrease in steatosis." (PMID 24587847, 2013).
visceral leishmaniasis (10 papers, 2012 to 2024). A severe form of leishmaniasis characterized by irregular bouts of fever, substantial weight loss, swelling of the spleen and liver, and anemia (which may be serious). "The intracellular pathogen Leishmania donovani, the cause of visceral leishmaniasis, exploits the host DUB A20, an NF-κB-responsive gene, to inhibit Toll-like-receptor 2 (TLR2)-mediated signaling in macrophages." (PMID 33277473, 2020). "In canine visceral leishmaniasis, peripheral monocytes TLR2+/CD11b+/CD14+ and hepatic macrophages CD11b+/CD18+ seem to be associated with lower tissue parasite load." (PMID 23668673, 2013). "On the other hand, monocytes isolated from patients with dermal sequelae of visceral leishmaniasis (post-kala-azar dermal leishmaniasis—PKDL) demonstrated decreased expression of TLR-2/4, simultaneous attenuation of ROS and increased expression of classic M2 markers (CD206, ARG1, and PPARγ)." (PMID 38743668, 2024). "Tlr2 has been reported as potential therapeutic target in visceral leishmaniasis." (PMID 34281214, 2021). "Few studies have evaluated TLR expression in visceral leishmaniasis, therefore, our results showing the increase of TLR2 after infection of monocytes by L. infantum, when compared with non-infected cultures, indicate that these receptors may also be involved in the recognition of the parasite." (PMID 29358935, 2017). "The relation of TLR2 and TLR4 in pro- and anti-inflammatory cytokine production was previously investigated in human patients with visceral leishmaniasis (VL)." (PMID 28288677, 2017). "On the other hand, there was an inverse correlation between the expression of TLR2-4 and that of IL-12 or IFN-γ, and parasite load, leading to the proposal that those TLRs are involved in the recognition of the parasite during visceral leishmaniasis." (PMID 22523644, 2012). "The consequences of TLR2 activation to the control of leishmaniasis was further verified using the TLR2 ligand, arabinosylated lipoarabinomannan (Ara-LAM), in a Balb/c model of visceral leishmaniasis." (PMID 22523644, 2012).
abscesses (9 papers, 2007 to 2023). "Alike our findings in the ENS, IL-17 significantly increased in abscesses of the central nervous system in TLR2ko mice, suggesting that the Tc17 infiltrate compensates the loss of TLR2-dependent signals in controlling infections." (PMID 30254622, 2018). "Strikingly, polymorphisms in TLR2 and TLR10 genes previously found to be associated with increased susceptibility to cSSSIs did not affect clinical severity as defined by lesion size in patients with major abscesses and DFIs in this study." (PMID 31786695, 2020). "Such T cell-independent proliferation of human B cells may be restricted to tissues with significant pathogen burden, for example, the draining lymph nodes of deep-seated abscess lesions, where SpA cross-linking of B cell receptors may trigger staphylococcal uptake and TLR2 activation." (PMID 33879590, 2021). "Compared with the healthy control, significant upregulation in the gene expression of CYP4F3, VEGF, IL-8, TLR2 (P < 0.0001), and MMP-9 (P < 0.001) was found in the abscesses." (PMID 34539639, 2021). "The TLR2-dependent lipoprotein recognition pathway does not appear to be critical for abscess susceptibility, since TLR2KO mice developed abscesses." (PMID 38096412, 2023). "More abscesses were noticed on the kidneys of TLR2−/− mice irrespective of age on day 10 after infection." (PMID 36808423, 2023). "In addition, cryptic abscesses and mucosal edema was more frequently observed in the colons of TLR1−/− and TLR2−/− mice than in those of TLR6−/− and wild-type C. albicans and DSS-treated mice." (PMID 28289440, 2017).
cerebral infarction (9 papers, 2009 to 2025). An ischemic condition of the brain, producing a persistent focal neurological deficit in the area of distribution of the cerebral arteries. "The protection of ischemic postconditioning on ischemia/reperfusion-induced cerebral infarction, cerebral edema and neurological dysfunction is associated with its attenuation of apoptosis, and inhibition of neuroinflammation via modulation of the TLR2 and TLR4 pathways." (PMID 24460643, 2014). "This study showed that brain infarct size was significantly less in TLR4(−/−) mice but was increased in TLR2(−/−) mice." (PMID 20628516, 2010). "We calculated the water content of brain tissue and the infarction size (as determined by TTC stain) to evaluate the influence of OMT on the expression of TLR4, TLR2, MyD88 and NF-κB in focal cerebral infarction in rats." (PMID 20182634, 2009). "After cerebral infarction, it has been confirmed that the infective injury around ischemic tissue becomes the direct cause of cerebral edema but does infective injury after cerebral infarction correlate to TLR4 and TLR2 levels?" (PMID 20182634, 2009). "This study investigated the relationship between anti-inflammatory responses of paeonol and signaling pathways of TLR2 and TLR4 in cerebral infarct." (PMID 28101118, 2016). "TLR2 and TLR4 knockout reduces inflammation, decreases the cerebral infarction area, and improves the neurological function score in MCAO mice; therefore, targeting the TLR signal may become an important treatment strategy for cerebral ischemic injury." (PMID 25928750, 2015).